FAM162A (family with sequence similarity 162 member A)
Description:
Proposed to be involved in regulation of apoptosis; the exact mechanism may differ between cell types/tissues. May be involved in hypoxia-induced cell death of transformed cells implicating cytochrome C release and caspase activation (such as CASP9) and inducing mitochondrial permeability transition. May be involved in hypoxia-induced cell death of neuronal cells probably by promoting release of AIFM1 from mitochondria to cytoplasm and its translocation to the nucleus; however, the involvement of caspases has been reported conflictingly (By similarity).
Synonyms: HGTD-P; C3orf28; E2IG5
Tractability: Antibody: UniProt predicts a signal peptide or a membrane-spanning region. PROTAC: ubiquitination databases record sites on it; its protein half-life has been measured.
Gene: Protein-coding gene on chromosome 3 (122,384,161 to 122,412,334, forward strand). Ensembl gene ENSG00000114023.
Subcellular location: Mitochondrion membrane
Subcellular location (Human Protein Atlas): Mitochondria
Gene Ontology:
Molecular function: protein binding
Biological process: cellular response to hypoxia; positive regulation of apoptotic process; positive regulation of release of cytochrome c from mitochondria; neuron apoptotic process
Cellular component: mitochondrial membrane; mitochondrion
Genetic constraint (gnomAD): Loss-of-function variants: 13 observed, 12.4 expected, observed/expected ratio (o/e) 1.05, 90% interval 0.68 to 1.64. The upper end of that interval is the gene's LOEUF score, 1.64, which puts it in group 6 of 6, group 1 being the genes least tolerant of losing a copy. Missense variants: 125 observed, 135.8 expected, observed/expected ratio (o/e) 0.92, 90% interval 0.8 to 1.07. Synonymous variants: 40 observed, 43.78 expected, observed/expected ratio (o/e) 0.91, 90% interval 0.71 to 1.19.
Homologues: Orthologues: chimpanzee FAM162A (99% identical), macaque FAM162A (88% identical), pig FAM162A (84% identical), rabbit FAM162A (82% identical), dog FAM162A (81% identical), mouse Fam162a (79% identical), guinea pig FAM162A (75% identical), rat Fam162a (71% identical), tropical clawed frog fam162a (46% identical), Drosophila melanogaster CG9231 (28% identical), Caenorhabditis elegans taap-1 (18% identical). Paralogues in human: FAM162B (40% identical).
Diseases named in the same sentence as FAM162A in open-access papers:
FAM162A is named in the same sentence as 24 diseases in open-access papers, as found by Europe PMC text mining. Sharing a sentence is not in itself a finding about the gene and the disease. The quoted sentences say what the papers report.
heart failure (2 papers, 2020 to 2021). Inability of the heart to pump blood at an adequate rate to meet tissue metabolic requirements. "Specifically, FAM162A transcript levels were upregulated in several mouse disease models including transverse aortic constriction-induced (TAC) heart failure, myocardial infarction, and hypertrophic cardiomyopathy." (PMID 33262348, 2020). "In an attempt to establish the link between altered expression and human heart diseases, we performed immunoblot analysis of FAM162A, MCT1, and COX20 to investigate protein levels in human hearts from patients with clinical DCM and ICM, the two most common etiologies of heart failure." (PMID 33262348, 2020). "We have provided further compelling evidence suggesting that some of our prioritized rank-ordered list of proteins, including FAM162A, MCT1, and COX20 are cardiac enriched, localized within subcellular compartments, and may play a role in the progression of heart failure." (PMID 33262348, 2020).
ischemic cardiomyopathies (2 papers, 2020 to 2023). "FAM162A may serve as possible therapeutic and diagnostic targets for human dilated and ischemic cardiomyopathies because it was differentially expressed at the transcriptomic and proteomic levels in a number of rodent and human heart disease models." (PMID 37637145, 2023). "FAM162A, MCT1, and COX20 were expressed differentially at the transcriptomic and proteomic levels in multiple models of mouse and human heart diseases and may represent potential diagnostic and therapeutic targets for human dilated and ischemic cardiomyopathies." (PMID 33262348, 2020). "Consistent with the mouse data, an increased expression of FAM162A was observed in human dilated cardiomyopathy (DCM), idiopathic cardiomyopathy, and ischemic cardiomyopathy (ICM), albeit not significantly." (PMID 33262348, 2020).
myocardial infarction (2 papers, 2020 to 2023). Gross necrosis of the myocardium, as a result of interruption of the blood supply to the area, as in coronary thrombosis. "Of the 4 hub genes, ADM was upregulated in CAD (GSE56885), PPFIA4 and TPBG were upregulated in patients with ischemic heart disease (GSE48166), and FAM162A was downregulated in patients with myocardial infarction (GSE141512)." (PMID 37637145, 2023).
osteosarcoma (2 papers, 2022 to 2024). A usually aggressive malignant bone-forming mesenchymal neoplasm, predominantly affecting adolescents and young adults. "We developed a new prognostic risk model for osteosarcoma based on 7 glycolytic genes (INSR, FAM162A, GLCE, ADH5, G6PD, SDC3, HS2ST1) by bioinformatics." (PMID 36387908, 2022). "A risk model based on seven glycolytic genes (INSR, FAM162A, GLCE, ADH5, G6PD, SDC3, HS2ST1) can effectively evaluate the prognosis of osteosarcoma, and in vitro experiments also confirmed the important role of INSR in promoting OS migration." (PMID 36387908, 2022). "According to the Kaplan-Meier (KM) survival analysis of 8 modeled genes, elevated expression levels of COL5A2, COX6A2, UQCRB, SFXN4, FAM162A and MAFF sharply shortened the survival time of osteosarcoma patients." (PMID 39569192, 2024). "Multivariate Cox regression analysis confirmed that these 8 identified genes, including 2 protective elements (SQOR and PFKFB2) and 6 hazardous factors (MAFF, COL5A2, FAM162A, UQCRB, SFXN4, and COX6A2), could independently predict the overall survival of osteosarcoma samples." (PMID 39569192, 2024).
prostate carcinoma (2 papers, 2020 to 2021). A carcinoma that arises from epithelial cells of the prostate gland. "For example, relevant studies demonstrated that FAM162A overexpression induces canonical mitochondrial cell death in multiple cells, including prostate cancer cells." (PMID 34367470, 2021). "Specifically, in vitro overexpression of FAM162A induces canonical mitochondrial cell death in prostatic cancer cells and human alveolar epithelial cells." (PMID 33262348, 2020).
alcohol dependence (1 paper, 2020). Physical and psychological dependence on alcohol. "FAM162A is associated by GWAS to a gene-by-alcohol dependence interaction study of risky sexual behaviors and so it could be related to behavioral control." (PMID 33115496, 2020).
lung adenocarcinoma (1 paper, 2023). A carcinoma that arises from the lung and is characterized by the presence of malignant glandular epithelial cells.
lung squamous cell carcinoma (1 paper, 2024). "FAM162A has been incorporated into the prediction model of lung squamous cell carcinoma, and its expression has been taken into account for calculating the m6A score to predict the immunotherapy response of patients." (PMID 39569192, 2024).
ovarian carcinoma (1 paper, 2020). A malignant neoplasm originating from the surface ovarian epithelium. "The RT-qPCR results showed that compared with human ovarian epithelial cells, the expression of B3GAT3, COL5A1, FAM162A, IDUA, and PPP2R1A in ovarian cancer cells was significantly downregulated." (PMID 33281878, 2020). "We further analyzed the differential expression of B3GAT3, COL5A1, FAM162A, IDUA, and PPP2R1A in ovarian cancer SKOV-3 and A2780 cells and HOSEpiC human ovarian epithelial cells." (PMID 33281878, 2020).
cancer (2 papers, 2020 to 2022). A tumor composed of atypical neoplastic, often pleomorphic cells that invade other tissues. "However, the specific roles of SEC13, ALG1, FAM162A, GALK1, and XYLT2 in cancer remain unclear." (PMID 35963622, 2022).
heart disease (2 papers, 2020 to 2023). "To assess for any correlation to cardiac disease, we performed a query of publicly available GEO RNA-Seq datasets containing data for human and mouse cardiovascular diseases to determine expression levels of FAM162A, MCT1, and COX20." (PMID 33262348, 2020). "Similarly, an upregulation of FAM162A in human DCM hearts suggests its specific role in modulating the etiologies of this specific heart disease characterized by dilated and impaired ventricular contraction." (PMID 33262348, 2020). "In addition to the phenotypic analysis using the mouse genome informatics data, no known human mutations of FAM162A, MCT1, and COX20 have been linked to classical human heart diseases." (PMID 33262348, 2020).
FAM162A also shares sentences with these, for which no sentence is quoted: malaria (2 papers); Alzheimer disease (1); bipolar disorder (1); cardiovascular diseases (1); colon disease (1); dilated cardiomyopathy (1); glioma (1); hypertrophic cardiomyopathy (1); idiopathic cardiomyopathy (1); ischemia (1); periodontitis (1); Sepsis (1); tumor (1).